PGR (progesterone receptor)
Diseases named in the same sentence as PGR in open-access papers (continued):
Sharing a sentence is not in itself a finding about the gene and the disease.
triple-negative breast carcinoma (1,118 papers, 2008 to 2026). An invasive breast carcinoma which is negative for expression of estrogen receptor (ER), progesterone receptor (PR), and human epidermal growth factor receptor 2 (HER2). "Only 14% of triple negative breast cancers carry this mutation whilst it is present in 32% of estrogen and progesterone receptor positive cancers." (PMID 36635367, 2023). "High BMI is associated with decreased risk of estrogen receptor– and progesterone receptor–positive (ER + PR+) premenopausal breast cancers, but it is also associated with increased risk of premenopausal triple-negative breast cancer in African American women." (PMID 26526858, 2015). "The patient with this mutation was 53 years old and diagnosed with triple-negative breast cancer because estrogen receptor (ER), progesterone receptor (PR), and human epidermal growth factor receptor type 2 (HER2) were negative in immunohistochemistry (IHC) and fluorescence in situ hybridization." (PMID 31700649, 2019). "We were interested in whether MDA-MB-231, which is a triple-negative breast cancer cell line having reduced expression of estrogen receptor (ER), progesterone receptor, and HER249, was susceptible to cell death upon combination exposure of paclitaxel, Atezolizumab, and NK92-CD16 cells." (PMID 34290356, 2021). "Breast tumor cells that lack the expression of human epidermal growth factor receptor 2 (HER2), the progesterone receptor (PR), and the estrogen receptor (ER) define a subgroup of breast cancer as triple-negative breast cancer (TNBC)." (PMID 41487836, 2025). "Using FIBIS, we show that normal epithelial mitochondria uptake alters the free NADH-to-bound NADH ratio, increasing bound NADH in both estrogen- and progesterone receptor-positive and triple-negative breast cancer cells." (PMID 41355665, 2025). "Unlike BRCA2 mutation carriers, who are more likely to develop tumors that are progesterone receptor (PR)- or estrogen receptor (ER)-positive, BRCA1 mutation carriers predominantly develop triple-negative breast cancer (TNBC)." (PMID 39997609, 2025). "Hs578t is a cell line that represents triple-negative breast cancer, as it lacks estrogen receptor, progesterone receptor, and human epidermal growth factor receptor 2 (HER2)." (PMID 40042717, 2025). "The molecular diagnosis of triple-negative breast cancer is primarily based on the IHC of the estrogen receptor (ER), progesterone receptor (PR), and human epidermal growth factor receptor 2 (HER2)." (PMID 37445737, 2023). "Triple-negative breast cancers (TNBCs) are tumors that lack expression of the estrogen receptor (ER), progesterone receptor (PR), and HER2, and account for approximately 15–20% of all diagnosed breast tumors." (PMID 37592347, 2023). "MDA-MB-231 is a triple-negative breast cancer cell line that lacks the expression of estrogen receptor (ER−), progesterone receptor (PR−), and human epidermal growth factor receptor 2 (HER2−)." (PMID 36986815, 2023). "Since triple negative breast cancer is known to have a poor prognosis, ER (Estrogen Receptor), PR (Progesterone Receptor), and HER-2 (Human Epidermal growth factor Receptor 2) are highly relevant markers." (PMID 37415138, 2023). "It is a new therapeutic target for triple-negative breast cancer, which is transcriptionally regulated by estrogen receptor-alpha, human epidermal growth factor receptor 2, and the progesterone receptor." (PMID 35812749, 2022). "Thirty patients (35%) had triple-negative breast cancer, which was defined as oestogren and progesterone receptor levels of less than 1%, and HER2-negative." (PMID 35246547, 2022). "MDA-MB231 cells are the best-studied triple-negative breast cancer cell line (estrogen receptor (ER)-, progesterone receptor (PR)-, HER2-)." (PMID 36143471, 2022). "Triple-negative breast cancer is an aggressive form of invasive breast cancer defined by the lack of significant expression of the therapeutic target estrogen receptor, progesterone receptor and HER2119." (PMID 36163484, 2022).
triple-negative breast carcinoma (continued). "The take rate exceeds 50% in triple-negative breast cancer, which is an aggressive subtype; in contrast, the take rate in the estrogen (ER)- or progesterone receptor (PR)-positive subtype, which is relatively indolent, is usually less than 10%." (PMID 33407601, 2021). "In hormone receptor status, the majority of HER2-negtive MBC patients were estrogen receptor (ER) positive and / or progesterone receptor (PR) positive, but the minority is patients with triple negative breast cancer." (PMID 32131770, 2020). "Triple negative breast cancers (TNBCs) lack estrogen receptor (ER), progesterone receptor (PR), and human epidermal growth factor receptor 2 (HER2) expression and account for approximately 15-25% of total breast cancer cases." (PMID 33123316, 2020). "Triple-negative breast cancers (TNBCs) are defined as tumors that lack the expression of estrogen receptor (ER), progesterone receptor (PR), and human epidermal growth factor receptor 2 (HER2)." (PMID 31907878, 2020). "Triple-negative breast cancer (TNBC) is a special type of breast cancer that is characterized by the progesterone receptor (PR), estrogen receptor (ER), and human epidermal growth factor receptor 2 (HER2), all of which are negative." (PMID 33536908, 2020). "This leading deadly disease is generally divided into luminal A, luminal B, HER2/ErbB2-positive, and triple-negative breast cancer subtypes according to the expression status of estrogen receptor, progesterone receptor, and HER2/ErbB2." (PMID 30786890, 2019). "Identification of novel targets for triple-negative breast cancer (TNBC) is an urgent task as targeted therapies have increased the lifespans of Oestrogen Receptor +/ Progesterone Receptor + and HER2+ cancer patients." (PMID 31588230, 2019). "Triple negative breast cancers (TNBCs) are known to express low PGR, ESR1, and ERBB2, and high KRT5, KRT14, and KRT17." (PMID 30335837, 2018). "In particular, FOXC1 is a prognostic biomarker for BLBC, which is a form of triple-negative breast cancer for estrogen receptor (ER), progesterone receptor (PR), and human epidermal growth factor receptor 2 (HER2)." (PMID 30564302, 2018). "A subset of 15–20% of breast tumors lacks ER, HER-2 and progesterone receptor (PR) and this subtype is classified as triple negative breast cancer (TNBC)." (PMID 29533973, 2018). "Higher PD-L1 expression in tumor cell was related to larger tumor size, estrogen receptor negativity, progesterone receptor negativity, human epidermal growth factor type-2 positivity, and triple-negative breast cancer." (PMID 29041905, 2017). "Patients with triple-negative breast cancer for oesterogen receptor (ER)-, progesterone receptor (PR),- and HER2- have a poor prognosis as they frequently develop metastasis." (PMID 28105072, 2016). "Triple-negative breast cancers (TNBCs) are defined as tumors that lack expression of estrogen receptor (ER), progesterone receptor (PR), and HER2." (PMID 26561834, 2015). "MDA-MB-231 cells exemplify the class of triple-negative breast cancers (TNBCs), which lack expression of the estrogen receptor (ER), progesterone receptor, and human epidermal growth factor receptor 2 (HER2)." (PMID 25238333, 2014). "The lesion was considered to be an SCC demonstrating negative expression for the human epidermal growth factor receptor 2, estrogen receptor and progesterone receptor; therefore, the tumor was a triple-negative breast cancer." (PMID 24520287, 2014). "Conversely, PGR, PDK1, and PEA15 are associated with Luminal A. Interestingly, in triple-negative breast cancer and ovarian cell lines, increasing PEA15 levels was shown to have an antitumor effect." (PMID 25183703, 2014). "Triple-negative breast cancers (TNBCs), which lack the expression of estrogen receptor (ER) and progesterone receptor (PR) and the amplification of the HER2 gene, are a clinically aggressive and molecularly diverse type of breast cancer." (PMID 24485087, 2014).
triple-negative breast carcinoma (continued). "The relative PCho area was significantly higher in ER+/PgR+ samples than in samples from triple negative breast cancer." (PMID 20716336, 2010). "In order to evaluate if the xenograft models are representative for human disease, the metabolic profiles were compared to corresponding profiles from patients with ER+/PgR+ or triple negative breast cancer." (PMID 20716336, 2010). "The relevance of the basal-like and luminal-like xenografts used in this study was further supported by comparing the choline metabolite pattern with that of human tissue samples from ER+/PgR+ and triple negative breast cancer." (PMID 20716336, 2010). "Furthermore, 70% of BRCA1-associated breast cancers are triple-negative breast cancer (TNBC): estrogen receptor (ER)-, progesterone receptor (PR)-, and HER2-negative cancers." (PMID 41283387, 2025). "Statistical correlations were established between tumor budding and tumor size, histological grade, lymph node involvement, vascular invasion, and molecular subtypes (estrogen receptor, progesterone receptor, human epidermal growth factor receptor 2, and triple-negative breast cancer, TNBC)." (PMID 39469410, 2024). "This cell line represents a highly aggressive, invasive, and poorly differentiated triple-negative breast cancer cell line, as it lacks estrogen receptor (ER) and progesterone receptor (PR) expression, as well as HER2 (human epidermal growth factor receptor 2) amplification." (PMID 38927055, 2024). "Triple-negative breast cancer (TNBC), characterized by the loss of expression of the estrogen receptor (ER), progesterone receptor (PR), and human epidermal growth factor 2 (HER2), is the most aggressive subtype, with early recurrence and unfavorable prognosis." (PMID 38957805, 2024). "BC can be categorized into four different subtypes based on the expression of the Human epidermal growth factor receptor (HER2/neu), the estrogen receptor (ER), and the progesterone receptor (PR): triple negative breast cancer (TNBC), Luminal A, Luminal B, and HER2 (+)." (PMID 37465670, 2023). "SK-N-SH is a cancer cell line that display epithelial morphology, while MDA-MB-231 is an aggressive, highly invasive, and triple-negative breast cancer cell line that lacks an estrogen receptor, progesterone receptor, and human epidermal growth factor receptor-2." (PMID 37050098, 2023). "Triple negative breast cancer, which accounts for 10–20% of all invasive breast cancer (BC) subtypes, is characterized by the lack of immunohistochemical expression of estrogen receptor (ER), progesterone receptor (PR), and HER2 and/or HER2 gene amplification." (PMID 36030436, 2023). "Predominantly patients (73.8%) were hormone positive (either oestrogen receptor (ER) or progesterone receptor (PR) or both) and of luminal A or B subtype, followed by 70 (18.2%) and 31 (8.3%) patients each in triple-negative breast cancer (TNBC) and HER2 enriched subtypes." (PMID 37377682, 2023). "The majority of BRCA1-deficient breast cancer cases are classified as triple-negative breast cancer based on the absence of expression of estrogen receptor (ER), progesterone receptor (PR), and HER29, and targeted therapy for this type of cancer is difficult." (PMID 32978388, 2020). "Breast cancer is commonly categorized by hormone receptor expression and can be classified into distinct groups: estrogen receptor-positive (ER+), human epidermal growth factor receptor 2-positive (HER2+), progesterone receptor-positive (PR+), or triple-negative breast cancer (TNBC)." (PMID 32023849, 2020). "Interestingly, a preponderance of these ER-GPER+ tumors are triple negative breast cancers that lack ER, progesterone receptor (PR) and her2/neu." (PMID 33329395, 2020).
triple-negative breast carcinoma (continued). "High tumour cell PDGFRα expression has been linked to lymph node metastasis, human epidermal growth factor receptor 2 (HER2) positivity, high histologic grade, oestrogen receptor (ER) negativity, progesterone receptor (PR) negativity and the triple-negative breast cancer subtype (TNBC)." (PMID 29380207, 2018). "Moreover, AR stimulates cellular proliferation in triple negative breast cancer (ERα –, PgR –, and HER-2-Neu –)." (PMID 30210453, 2018). "Furthermore, triple negative breast cancer cell lines, which lack estrogen receptor (ER), progesterone receptor (PR) and human epidermal growth factor receptor (HER2/neu), express metabotropic glutamate receptor 1, mGluR1." (PMID 28231291, 2017). "Given the emergence of triple-negative breast cancer as a distinct clinical entity, designers of clinical trial matching systems should include progesterone receptor status in their matching criteria and prompt patients to ask their physicians about it if necessary." (PMID 22784878, 2012). "These tumors may share clinical and biologic properties with triple negative breast cancers (TNBCs) that lack expression of ER, progesterone receptor (PgR) and HER2." (PMID 20920367, 2010). "Our patient had triple-negative breast cancer with regard to ER, PgR and Her2." (PMID 18559079, 2008). "Importantly, cell lines representing triple negative breast cancers that lack clinically useful receptors (estrogen receptor, progesterone receptor, human epidermal growth factor-2) have higher endogenous levels of ROS and are thus more sensitive than their receptor-positive counterparts." (PMID 33202842, 2020). "Additionally, the MCF-10A cells with added mutations begin to model triple-negative breast cancer, since these cells do not express the estrogen receptor (ER) or progesterone receptor (PR), nor do they overexpress Her2/Neu." (PMID 29848992, 2018). "Besides its effect on CSCs, TGFβ may particularly affect triple-negative breast cancers, a subtype devoid of estrogen receptor, progesterone receptor and Her2." (PMID 23349840, 2013). "Triple-negative breast cancers (TNBCs) are tumors, nominally classified as a diagnosis of exclusion, that do not express clinically significant levels of the estrogen receptor (ER), progesterone receptor (PgR) and epidermal growth factor receptor 2 (Her-2) over-expression or gene amplification." (PMID 24205362, 2013). "Estrogen receptor (ER) positivity was noted in 62.9%, progesterone receptor (PR) positivity in 57.1%, human epidermal growth factor receptor 2 (HER2/neu) overexpression in 25.7%, and triple-negative breast cancer in 17.1% of cases." (PMID 41684983, 2026). "Among its subtypes, triple-negative breast cancer (TNBC) remains a major clinical challenge as it lacks estrogen receptor (ER), progesterone receptor (PR), and human epidermal growth factor receptor 2 (HER2)." (PMID 40943370, 2025). "Triple-negative breast cancer (TNBC) is an aggressive and heterogeneous subtype of breast cancer that lacks the expression of estrogen receptor (ER), progesterone receptor (PR), and human epidermal growth factor receptor 2 (HER2)." (PMID 40277915, 2025). "These subtypes include estrogen receptor-positive (ER+), progesterone receptor-positive (PR+), Human epidermal growth factor receptor-2-positive (HER2+), and triple-negative breast cancer (TNBC)." (PMID 40821783, 2025). "Triple-negative breast cancer (TNBC) accounts for 15-20% of breast cancer cases and lacks expression of estrogen receptor (ER), progesterone receptor (PR), and human epidermal growth factor receptor 2 (HER2)." (PMID 40730501, 2025). "Nearly 15% of invasive breast cancers are devoid of estrogen receptor (ER), progesterone receptor (PR), and human epidermal growth factor receptor type 2 (HER2) expression and, thus, defined as triple-negative breast cancer (TNBC)." (PMID 40282497, 2025).
triple-negative breast carcinoma (continued). "Triple-negative breast cancer (TNBC) is a type of breast cancer that lacks the expression of estrogen receptor (ER), progesterone receptor (PR), and human epidermal growth factor receptor 2 (HER2) and has high malignancy, easy metastasis, and poor prognosis." (PMID 40059196, 2025). "Clinically, breast cancer is categorized by estrogen receptor (ER), progesterone receptor (PR), and HER2 expression into hormone receptor (HR)-positive (~75%), HER2-positive (~10%), and triple-negative breast cancer (TNBC, 10–15%)." (PMID 41462902, 2025). "Breast cancer is clinically categorized into three primary subtypes: estrogen receptor/progesterone receptor (ER/PR)-positive, human epidermal growth factor receptor 2 (HER2)-positive, and triple-negative breast cancer (TNBC)." (PMID 40432130, 2025). "Triple-negative breast cancer (TNBC) tumors lack detectable estrogen receptor (ER), progesterone receptor (PR), and human epidermal growth factor receptor 2 (HER2) gene amplification." (PMID 38579004, 2024). "Of the patients, 57.6%, 50.0% and 37.3% were oestrogen receptor (ER) positive, progesterone receptor (PR) positive and HER2 positive, respectively, and 16.7% of them were diagnosed with triple-negative breast cancer." (PMID 38347468, 2024). "The disease is classified into distinct subtypes based on the expression of estrogen receptor (ER), progesterone receptor (PR), and human epidermal growth factor receptor-2 (HER2): Luminal A, Luminal B, HER2, and triple-negative breast cancer (TNBC)." (PMID 39234109, 2024). "Triple-negative breast cancer (TNBC) is an aggressive subset of breast cancer that lacks expression of the estrogen receptor (ER), progesterone receptor (PR), and human epidermal growth factor receptor 2 (HER2)." (PMID 38791148, 2024). "Triple-negative breast cancer (TNBC), which lacks the expression of estrogen receptor, progesterone receptor, and human epidermal growth factor receptor 2 (HER2), is the most aggressive subtype." (PMID 39194515, 2024). "MDA-MB-231 lacks ER, progesterone receptor (PR), and HER2 and is in the triple-negative breast cancer (TNBC) subtype." (PMID 39459017, 2024). "Triple negative breast cancer (TNBC) is a heterogeneous group of tumors which lack estrogen receptor, progesterone receptor, and HER2 expression." (PMID 38229082, 2024). "Triple-negative breast cancer (TNBC) is an aggressive breast cancer subtype that is devoid of the expression of the estrogen receptor (ER), progesterone receptor (PR) and human epidermal growth factor receptor 2 (HER2)." (PMID 39502536, 2024). "Triple-negative breast cancers (TNBC) are defined as tumors that lack the expression of the estrogen receptor (ER), progesterone receptor (PR), and human epidermal growth factor receptor 2 (HER2)." (PMID 40860264, 2024). "Several subtypes of breast cancers, including estrogen receptor (ER)-positive, progesterone receptor (PR)-positive, human epidermal growth factor 2 receptor-positive (HER-2), and triple-negative breast cancer (TNBC) are known." (PMID 38893132, 2024). "According to the expression of estrogen receptor (ERα), progesterone receptor (PR), and human epidermal growth factor receptor (HER2), breast cancer is divided into ER/PR-positive, HER2-positive, and triple-negative breast cancer (TNBC)." (PMID 37787041, 2023). "Clinically, using estrogen receptor (ER), progesterone receptor (PR) and human epidermal growth factor receptor 2 (HER2) as markers, breast cancer patients are mainly classified into ER+, HER2 + and triple-negative breast cancer (TNBC) subtypes." (PMID 37280526, 2023). "Triple-negative breast cancer (TNBC) is defined as breast cancer that lacks the expression of an estrogen receptor (ER), progesterone receptor (PR), and human epidermal growth factor receptor 2 (HER2)." (PMID 37512096, 2023).